IL13 (interleukin 13)
Diseases named in the same sentence as IL13 in open-access papers (continued):
Sharing a sentence is not in itself a finding about the gene and the disease.
Insulin resistance (continued). "However, IL-13 serum levels have not been assessed in subjects with insulin resistance, and associations of IL-13 with parameters of low-grade systemic inflammation are still unknown." (PMID 29675435, 2018). "Patients with insulin resistance also have elevated serum IL-13 levels, although the level does not correlate with markers of systemic inflammation." (PMID 37629063, 2023). "Hyperglycemia—but not insulin resistance or metabolic dysfunction—was only observed in BALB/c-IL13-knockout mice on a Western diet." (PMID 37629063, 2023). "This study demonstrates that IL-13 serum levels are elevated in patients with insulin resistance without showing correlation with parameters of low-grade systemic inflammation." (PMID 29675435, 2018). "Notably, ninety-five percent of low-IL-13 producers showed a HOMA-IR value below 3, whereas an inverse tendency was seen in high-IL-13 producers that exhibited increasing levels of insulin resistance (HOMA-IR > 4.5)." (PMID 29675435, 2018). "For IL13, we found a significant inverse correlation to body weight, body fat, and waist circumference, whereas IL4 expression inversely correlated with waist circumference, fasting plasma glucose (FPI), and homeostatic model assessment for insulin resistance (HOMA-IR) in visceral WAT." (PMID 36982747, 2023). "Therefore, our results reveal that serum levels of IL-13 elevate in insulin resistance without showing correlation with markers of low-grade systemic inflammation in humans." (PMID 29675435, 2018). "Nevertheless, we have drawn a speculative hypothesis to explain the apparently contradictory results regarding the role of IL-13 in the development of insulin resistance, and the discussion of this information makes no attempt to conjecture beyond that." (PMID 29675435, 2018).
rheumatoid arthritis (28 papers, 2005 to 2025). A chronic, systemic autoimmune disorder characterized by inflammation in the synovial membranes and articular surfaces. "IL-5 enhances the production of B1 cells which are anti-inflammatory (impaired B1 cells have been found in multiple sclerosis, systemic lupus erythematosus, and rheumatoid arthritis), and IL-13 has anti-inflammatory properties." (PMID 40284540, 2025). "IL-13 (and IL-4) belong to the T helper 2 (Th2) cytokine family and have been shown to play a role in downmodulating inflammatory responses in rheumatoid arthritis, induce macrophage polarization from a pro-inflammatory M1 to an anti-inflammatory M2 phenotype." (PMID 38585987, 2024). "IL-13 has been reported to increase in plasma, synovial fluid and muscular micro dialysate of patients with rheumatoid arthritis and jaw muscle pain, respectively." (PMID 32185190, 2020). "IL-13, which has been shown to protect synoviocytes from apoptosis in rheumatoid arthritis, was upregulated by treatment with vehicle alone and further increased by 24R,25(OH)2D3, which demonstrates the complexity of events in the knee joint." (PMID 27575371, 2016). "15-LO-1 expression is induced by IL-13 in human blood monocytes and by IL-4 in monocytes, alveolar macrophages, dendritic cells, mast cells and rheumatoid arthritis synovial cells." (PMID 19497113, 2009). "In contrast, IL-13 is expressed in rheumatoid arthritis synovial fluid and synovial fluid macrophages and resembles many functions of IL-4." (PMID 15743487, 2005). "In addition, IL-13 gene therapy in rheumatoid arthritis synovium reduced inflammatory cytokines and prostaglandin E2." (PMID 27095999, 2015). "Rheumatoid arthritis (RA) animal study proposed that MA can effectively stimulate adaptive immune cytokines, such as IL-4 and IL-13, to repair RA damage." (PMID 36712435, 2022). "IL-13 levels were also not significantly different between three genotypes, however, there was a trend to higher levels in FliiTg/Tg mice OVA-induced AD-like skin lesions and IL-13 cytokine has previously been linked to autoantibody production in early rheumatoid arthritis." (PMID 30147695, 2018).
idiopathic pulmonary fibrosis (25 papers, 2008 to 2025). Idiopathic pulmonary fibrosis (IPF) is a nonneoplastic pulmonary disease that is characterized by the formation of scar tissue within the lungs in the absence of any known cause. "Finally, over expression of IL-13 has also been implicated in the development of other fibrotic diseases including idiopathic pulmonary fibrosis (IPF)." (PMID 18348727, 2008). "By degrading the mRNA of transcription factors Gata3 and Egr1, it indirectly suppresses the production of pro-fibrotic cytokines such as IL-5 and IL-13, thereby limiting the progression of idiopathic pulmonary fibrosis (IPF)." (PMID 41154702, 2025). "Human alveolar macrophages (AMs) express high levels of interleukin (IL)-10, IL-13, and platelet derived growth factor (PDGF) in patients with idiopathic pulmonary fibrosis (IPF) and SSc." (PMID 35729674, 2022).
lung carcinoma (23 papers, 2010 to 2025). "IL-33 and IL-13 have been implicated in the progression of other cancers, such as breast and lung cancers." (PMID 40761291, 2025). "In contrast, IL-18 was inversely associated with lung cancer, while IL-13 showed a direct correlation." (PMID 39267832, 2024). "The adverse evidence of IL-13 in lung cancer primarily lies in its association with tumor development and prognosis." (PMID 39267832, 2024). "We next examined IL-4, IL-5, IL-6, and IL-13 levels in BAL, since IL-4, IL-5, and IL-13 are major mediators of allergic inflammation and IL-6 gene polymorphisms have been associated with increased lung cancer risk in asthmatics." (PMID 20796309, 2010). "The cytokines produced by “Type 2” immune cells (including ILC2s), IL-5, IL-13 and IL-4, were increased in both PLs and mPEs from lung cancer patients as compared to HD PLs." (PMID 40993215, 2025). "IL-13, a cytokine that regulates various cellular functions and immune responses by binding to its receptor, exhibits a dual role in lung cancer, inhibiting apoptosis and promoting tumor cell proliferation." (PMID 39267832, 2024). "In summary, our study identified two axes in the immune cell-inflammatory factor-lung cancer pathway, namely HLA DR on CD33dim HLA DR+ CD11b+ - Interleukin-18 - lung cancer and HLA DR on CD33dim HLA DR+ CD11b+ - Interleukin-13 - lung cancer." (PMID 39267832, 2024). "CHI3L1 regulates the IL-13 signaling pathway through IL-13Rα2, leading to increased secretion of cytokines, such as IL-1β and IL-6, which can influence inflammation in lung cancer." (PMID 38177294, 2024). "The IL-13 levels provided the following outcome for lung cancer (p = 4.56E-02; OR 95% CI = 1.13 (1.00, 1.28))." (PMID 39267832, 2024). "The IL-4 and IL-13 further stimulated the lung cancer cell A549 to secrete CCL26." (PMID 41294800, 2025). "The IL-4 and IL-13 stimulated the lung cancer cell A549 to secrete CCL26." (PMID 41294800, 2025). "Therefore, our research provides partial evidence for the adverse prognosis of IL-13 in lung cancer." (PMID 39267832, 2024). "However, despite the dual role of IL-13, inhibiting its activity can inhibit the growth and spread of tumor cells, making IL-13 a potential target for lung cancer treatment." (PMID 39267832, 2024). "Additionally, IL-18 levels were negatively correlated with lung cancer, whereas IL-13 levels were positively correlated with lung cancer." (PMID 39267832, 2024). "In conclusion, our results suggest that MCs may contribute to lung cancer-related thrombosis through the release of cytokines, including IL-13, SerpinE1, and Thrombopoietin, following the uptake of lung cancer cell-derived exosomes." (PMID 37143160, 2023). "IL-12 and IL-12p70 activate natural killer cells and alveolar macrophages, while IL-13, which was not evaluated in the current study, signifies natural killer cell activity and is linked to lung cancer progression and metastasis." (PMID 37373957, 2023). "Another evidence supporting the cancer-promoting phenotype of basophils is that, when basophils and lung cancer cell line A549 were cocultured together, the former could produce IL-13, which could in turn promote the proliferation and migration of the latter." (PMID 35445073, 2022). "Further, our group previously discovered that ISO treatment could enhance the radiosensitivity of lung cancer cells through the IL-13 and NF-κB signaling pathways." (PMID 36014431, 2022). "In addition, MAO-A expression, activity, and function are altered in IL-13-induced monocytes and in A549 lung carcinoma cells." (PMID 32872335, 2020). "Serum IL-13 was higher in lung cancer patients than that in healthy controls." (PMID 27605397, 2016). "In addition, IL-13 and IL-18 play an important role in the relationship between HLA DR expression on CD33dim HLA DR+ CD11b+ cells and lung cancer, and IL-18 plays an important role in lung cancer." (PMID 39267832, 2024).
lung carcinoma (continued). "The PI3Kγ inhibitor AS-605240, another top candidate, was found to suppress lung carcinoma inflammation and the secretion of pro-inflammatory cytokines (e.g. IL-17, IFN-γ, IL-22, GM-CSF, IL-6, IL-4, and IL-13)." (PMID 33381110, 2020). "For lung cancer, high intra-tumoral concentrations of CXCR2 ligands (CXCL1, CXCL5, and CXCL8) and type 2 cytokines IL-4, IL-5, IL-10, and IL-13 have been reported for non-small cell lung cancer." (PMID 26231039, 2015). "In addition, with the advent of a new monoclonal (Dupilumab) that blocks the shared receptor for Il-4 and IL-13 used in COPD patients with type 2 inflammation, the inflammation driving both COPD and lung cancer may help prevent the disease." (PMID 40149288, 2025). "Specifically, the expression of CD16-CD56 on NK T cells and HLA DR on CD33dim HLA DR+ CD11b+ cells exhibited a negative correlation with lung cancer, whereas the expression of HLA DR on CD33dim HLA DR+ CD11b+ cells was positively correlated with IL-18 and IL-13 levels." (PMID 39267832, 2024). "However, for lung cancer, the role of IL-13 has not been fully elucidated." (PMID 39267832, 2024).
lupus (23 papers, 2010 to 2025). "Excess IL-4 and IL-13 induce IgE class switching, which has been associated with the severity of lupus." (PMID 40534849, 2025). "Estrogens generally enhance humoral autoimmunity and stimulate the T-cell response typical of lupus, leading to increased production of cytokines such as IL-4, IL-5, IL-10, and IL-13." (PMID 40283389, 2025). "Pristane-induced lupus mice showed significantly higher serum levels of IL-1β, IL-2, IL-4, IL-13, IL-21, and IL-22 compared to those in WT mice." (PMID 35911685, 2022). "IL-13, one of the most important cytokines in the lupus, was believed to be a B-cell activating factor which resulted in the excessive production of many autoantibodies." (PMID 20706659, 2010). "IL-4 and IL-13, both induced by type 2 immune responses, were overexpressed in lupus mice." (PMID 35911685, 2022). "In addition, IL-2 expanded the IL-13-producing lupus CD8+ T cells that also expressed IL-5 and IFN-γ in association with STAT6 phosphorylation and GATA-3 expression, but not with STAT5 phosphorylation." (PMID 33763079, 2021). "While our understanding of lupus T cell biology has been rapidly evolving, it is unknown how IL-2 affects the lineage-specification of lupus T cells, and whether IL-13 plays a role in immune dysregulation in SLE." (PMID 33763079, 2021). "Lupus-associated and inflammatory cytokine genes, such as IL4, IL6, IL10 and IL13, are demethylated in lupus T cells and may contribute to disease progression." (PMID 25988383, 2015). "NK-cells play diverse functions in murine lupus producing cytokines such as IFN-γ, TNF-α, GM-CSF, interleukin (IL)-10, and IL-13 upon stimulation." (PMID 40806179, 2025). "In the early stages of lupus, the M1 pathway is mediated by cytokines including IFN-γ, whereas the M2 pathway is mediated by IL-4 and IL-13." (PMID 35733860, 2022). "On the other hand, IL-2 expanded IL-13-producing CD8+ T cells that also expressed IL-5 and IFN-γ in lupus patients via a signaling pathway likely involving the activation of STAT6-GATA-3 axis, but not STAT5." (PMID 33763079, 2021). "Our data collectively suggests that IL-2 induces IL-13, IL-5, and IFN-γ expression in lupus CD8+ T cells via STAT6-GATA-3 dependent mechanisms in contrast to the Treg differentiation in which IL-2-STAT5 axis plays a more essential role." (PMID 33763079, 2021). "Furthermore, dupilumab’s blockade of IL-4 and IL-13 may be ineffective, or even detrimental, in Th1-related disorders like systemic lupus erythematosus (SLE), potentially accelerating disease progression." (PMID 40151702, 2025). "Nonetheless, as such an antagonism has not been documented in CD8+ T cells, it is plausible that lupus CD8+ T cells employ a distinct molecular mechanism that allows for a dual IL-13- and IFN-γ expression." (PMID 33763079, 2021). "Moreover, the epigenetic mechanism of lupus suggests that the abnormal DNA hypomethylation of T cells results in the excessive expression of methylation-sensitive autoimmunity-related genes such as CD70, ITGAL, selectin-l, IL-4, and IL-13 in lupus." (PMID 33282947, 2020). "Similarly, our results revealed that in PBMC from SLE patients, several genes including CD70, ITGAL, selectin-l, and IL-13, all of which are hypomethylated and intensify lupus in different ways, are reduced by MSC." (PMID 33282947, 2020).
chronic asthma (22 papers, 2008 to 2025). An asthma that is characterized by the development of persistent airway inflammation and recurrent attacks of breathlessness and wheezing, which vary in severity and frequency. "Increased IL‐13 is associated with tissue remodeling and fibrosis by stimulating fibroblasts to synthesize collagen and also with activation of macrophages in chronic asthma." (PMID 27957328, 2016). "The quasi-absence of goblet cell hyperplasia and the reduced gene expression of Muc5ac, a gene linked to mucus secretion, in the MSC-treated IL-13 TG mice also indicated that Liproxstatin-1-primed hUC-MSCs exert anti-inflammatory effects in a murine model of chronic asthma." (PMID 35697721, 2022). "In contrast, in the chronic asthma model, each of the Th2 cytokine transcripts was modestly reduced in the sPLA2-deficient mice (i.e., reductions of 22% for IL-4, 19% for IL-5, an 49% for IL-13)." (PMID 23451035, 2013). "CycloZ effectively lowered the levels of Th2 cytokines (IL-4, IL-13) and related genes in both acute and chronic asthma models, pointing to its potent anti-inflammatory effects." (PMID 39682780, 2024). "BAL, lung tissue and faecal specimens were collected from IL-13 transgenic mice simulating chronic asthma to examine both the lower airway and gut microbiomes." (PMID 37110362, 2023). "IL-13 transgenic mice demonstrated phenotypes of chronic asthma, including severe inflammation, goblet cell hyperplasia, and subepithelial fibrosis." (PMID 35697721, 2022). "HE staining and ELISA detection results of inflammatory factors (IL-4, IL-5, and IL-13) showed that the inflammatory response was substantially higher in OVA-induced acute asthma (OVA-4 weeks group) than that in chronic asthma (OVA-8 weeks group)." (PMID 34671356, 2021). "IL-13 depletion can reduce sub-epithelial fibrosis and epithelial hypertrophy in chronic asthma model." (PMID 25472740, 2014). "Using a murine chronic asthma model with genetically modified transgenic (TG) mice that constitutively overexpress IL-13 in the lung, the study aimed to evaluate the anti-asthmatic effects of human umbilical cord-derived MSCs (hUC-MSCs) primed with Liproxstatin-1." (PMID 35697721, 2022). "Through in vivo studies with IL-13 TG mice displaying a majority of the features seen in chronic asthma patients, we confirmed the intratracheal delivery method retained anti-asthmatic abilities, while ensuring the absence of xenogeneic effects, as already proven by previous studies." (PMID 35697721, 2022). "However, the levels of IL-4, IL-5, and IL-13 substantially decreased in mice with chronic asthma compared with those in mice with acute asthma." (PMID 34671356, 2021). "However, treatment directed at TRPV1 significantly alleviated IL-4, IL-5, and IL-13 level in a chronic asthma murine model, while conversely TRPA1 promoted OVA-induced IL-4 production during acute allergic lung inflammation." (PMID 34099759, 2021). "In addition, our results demonstrated an increase in the levels of the main pro-inflammatory cytokines found in chronic asthma (IL-4, IL-5, and IL-13) and reduced the anti-inflammatory IL-10." (PMID 35185864, 2021). "Thus, Suhuang administration alleviates the pathological changes of chronic asthma likely through inhibition of IL-13 and TGF-β1." (PMID 26861679, 2016). "IL-13 TG mice simulate chronic asthma which may accompany long standing hypoxia." (PMID 33046682, 2020). "Both fungal extracts significantly elevated the IL-4, IL-5, IL-13, TNF-α, and TGF-β levels in mice with acute and chronic asthma." (PMID 40558541, 2025). "IL-13 is well-known for its role in mediating AHR and pathophysiological changes during chronic asthma." (PMID 37664635, 2023). "In mice chronic asthma models tiotropium significantly decreased smooth muscle thickening and peribronchial collagen deposition, with a parallel reduction of Th2-mediated cytokines such as IL5 and IL13." (PMID 29213218, 2017).